VEGFA (vascular endothelial growth factor A)
Diseases named in the same sentence as VEGFA in open-access papers (continued):
Sharing a sentence is not in itself a finding about the gene and the disease.
retinal diseases (235 papers, 2010 to 2026). "Intravitreal injection (IVI) of biologics that inhibit vascular endothelial growth factor A (VEGF-A) is a key treatment approach for retinal diseases in contemporary ophthalmology." (PMID 37936232, 2023). "Edema in DME and AMD can be significantly reduced with anti-VEGFA therapies; however, recent studies in the mouse suggest that global VEGFA blockade in retinal diseases might have detrimental side effects in the long-term." (PMID 33947161, 2021). "In this study, we aimed at in silico analysis of interaction of vascular endothelial growth factor A (VEGFA), the main mediator of angiogenesis, with binding domains of anti-angiogenic agents used for treatment of retinal diseases, such as ranibizumab, bevacizumab and aflibercept." (PMID 26578958, 2015). "However, there are still no evidences about a putative link in retinal disease between hypoxia, miRNAs, VEGFA, and TGFβ pathway." (PMID 32848728, 2020).
endometriosis (234 papers, 2006 to 2026). The growth of functional endometrial tissue in anatomic sites outside the uterine body. "Topological analysis demonstrated that major targets of S. Stoloniferum include IL-8, EGFR, TNF, and VEGFA, which are several of the causal genes of endometriosis." (PMID 33804660, 2021). "The VEGFA +936 C > T substitution is an important functional polymorphism that has been proven to alter susceptibility to various diseases that are linked to altered angiogenesis, including, endometriosis, cancer, and vascular and periaortic diseases." (PMID 28234972, 2017). "VEGFA is highest during menstruation in endometriosis compared with normal controls, is elevated in the PF of women with endometriosis, and promotes angiogenesis." (PMID 39836475, 2025). "Increased ANG, VEGFA, and sVEGFR-1 expression was previously observed in the peritoneal fluid of women with endometriosis." (PMID 38069001, 2023). "KLP, also called Kunling Wan, has been demonstrated to increase endometrial blood flow, upregulate vascular endothelial growth factor A, and inhibit angiogenesis and endometriosis induced by controlled ovarian hyperstimulation." (PMID 35668784, 2022). "VEGFA is the most potent and specific angiogenic factor, and it can increase cell proliferation, cell migration, and vascular permeability in endometriosis." (PMID 35130311, 2022). "The angiogenesis process is observed in endometriosis with several angiogenic factors involved, such as IL-8, VEGFA/C, and angiogenin in both clinic specimens and animal models." (PMID 34204039, 2021). "MiRNA-15a-5p downregulates vascular endothelial growth factor A, thus contributing to the pathogenesis of endometriosis." (PMID 33901012, 2021). "MiR-15a-5p, a negative regulator of VEGFA, has been found down-regulated in endometrium samples of woman with endometriosis and VEGFA was found up-regulated in the same endometrial tissues." (PMID 30037059, 2018). "Consequently, RNA interference (RNAi)-based angiogenic therapies targeting the VEGFA gene present a promising strategy for the treatment of endometriosis." (PMID 41226635, 2025). "In the literature, miR-93 (the precursor of miR-93-5p) has been shown to target Matrix Metalloproteinase 3 (MMP3) and Vascular Endothelial Growth Factor A (VEGF-A), which are involved in endometriosis by contributing to tissue remodeling, angiogenesis, and the proliferation of endometriotic lesions." (PMID 40305232, 2025). "Assessment of uNK, plasma cells, CD68+ macrophages, CXC-motif ligand 1 (CXCL1), CXC-motif receptor 2 (CXCR2), syndecan-1 and Vascular Endothelial Growth Factor A (VEGF-A) with immunohistochemistry has been used to map the endometrial immune environment in infertility patients with endometriosis." (PMID 38250081, 2023). "miRNA-15a-5p by regulating VEGFA in endometrial mesenchymal stem cells could contribute to the pathogenesis of endometriosis." (PMID 32850438, 2020). "ClusterB was revealed to be associated with significantly overexpressed VEGFA and VEGFC and, notably, downregulated ESR1 and PGR, which are characteristic biomarkers of endometriosis, indicating that clusterB might be highly linked to endometriosis." (PMID 36672827, 2022). "The expression level of miR-199a-5p in patients with endometriosis is significantly lower than that in normal people, and further studies have found that miR-199a-5p promotes the development of endometriosis by regulating VEGFA in endometrial mesenchymal stem cells." (PMID 35651811, 2022). "Thus, ferroptosis may play a critical role in the progression of endometriosis by resulting in angiogenic effects via paracrine VEGFA and IL8 action on the adjacent lesions." (PMID 35039492, 2022).
endometriosis (continued). "Eutopic endometrium of women with endometriosis has been reported to have disturbed angiogenic activity, as indicated by increased endothelial cell proliferation, higher microvessel density, and elevated levels of VEGFA, ANGPT1 and ANGT2 (Ang-1 and –2) mRNA, in comparison with that of healthy women." (PMID 34209508, 2021). "Moreover, the transfection of endometriosis stromal cells with miR-15a-5p mimics led to reduction in the expression of VEGFA and migration abilities of the endometrial stromal cells, suggesting an important role of this miRNA in the pathogenesis of endometriosis." (PMID 30037059, 2018). "The deregulation of miR-93 is believed to contribute to endometriosis by upregulating MMP3 and VEGFA, suggesting potential therapeutic targets." (PMID 40305232, 2025). "In animal models, curcumin has been shown to affect endometriosis through the HIF signaling pathway, whose key targets are HIF-1α, IL-6, and VEGFA, resulting in improved local hypoxia and reduced inflammation." (PMID 37375677, 2023). "We found that ferroptosis of ESCs induced VEGFA and IL8 secretion, and explored its potential effects on angiogenesis of adjacent lesions during the development of endometriosis." (PMID 35039492, 2022). "Among the top genes in the two key subnetworks, VEGFA, CXCL8, CCL2, IL1B and PTGS2 were also considered to be highly related to endometriosis in MalaCards." (PMID 35130311, 2022). "VEGFA and IL8 are pivotal angiogenic factors playing an essential role in the pathological progression of endometriosis." (PMID 35039492, 2022). "Various isoforms of VEGF, namely VEGFA, VEGF121, VEGF189, and VEGF111 have been found to be higher in peritoneal fluid during menstruation in women with endometriosis." (PMID 34717756, 2021). "Neoangiogenesis regulators such as Vascular Endothelial Growth Factor A (VEGFA) and Thrombospondin-1 (THBS1) have been involved in the pathology of endometriosis." (PMID 30037059, 2018). "Both Vascular Endothelial Growth Factor A (VEGF-A) and Thrombospondin-1 (TSP-1) represent the most potent pro- and anti-angiogenic factors, respectively, and have been involved in the pathology of endometriosis." (PMID 26771608, 2016). "First, EGCG was found to downregulate the expression of pro-angiogenic factors like vascular endothelial growth factor A (VEGF-A), vascular endothelial growth factor C (VEGF-C), and the tyrosine kinase receptor VEGF receptor 2 (VEGFR2) in murine endometriosis models." (PMID 36986169, 2023). "In an RNA sequencing study of control and endometriosis eutopic ESC- and endometrioma-derived sEV-RNA, hsa-miR-15a-5p, involved in vascular endothelial growth factor A (VEGF-A) downregulation, was lower in the cell culture supernatant of patients with endometriosis versus control." (PMID 37877421, 2023). "Numerous studies have shown that macrophages can produce angiogenic growth factors, including vascular endothelial growth factor A (VEGFA) and fibroblast growth factor 2 (FGF 2), which play a role in vascularization, accompanied by hypoxic environments such as tumors and endometriosis." (PMID 36865552, 2023). "We further investigated the location and expression of VEGFA and IL8 in endometriosis biospecimens." (PMID 35039492, 2022). "We also observed localised specific expression of VEGFA and IL8 in ectopic cysts and detected higher expression levels of VEGFA and IL8 in ectopic lesions, than in eutopic and control endometria in patients with endometriosis." (PMID 35039492, 2022). "The top 5 genes were the following: EGFR, EZH2, VEGFA, JUN, and FN1 with a degree >15; thus, they might be regulated by miR-200b-3p and play important roles in the progression of endometriosis." (PMID 32802844, 2020). "Several studies have reported an increase in VEGFA level in the serum and peritoneal fluid of endometriosis patients in comparison with women without the disease." (PMID 29937493, 2018).
endometriosis (continued). "Notably, VEGFA and IL8 showed localised expression and were significantly upregulated in ectopic lesions compared to control and eutopic endometrium samples from patients with endometriosis." (PMID 35039492, 2022). "Although VEGFA gene expression in the macrophages was changed, we could not identify whether this was the main mechanism, since the function of M1 macrophage is very complicated, and several factors might be involved in the inhibition of endometriosis." (PMID 34354711, 2021). "Moreover, the expression of VEGFA and IL8 in lesions was significantly higher than that in the eutopic and control samples, as detected using RT-qPCR and IHC, indicating that VEGFA and IL8 expression might be closely related to the pathogenesis of endometriosis." (PMID 35039492, 2022).
bladder cancer (230 papers, 2000 to 2026). "The results showed that the expression levels of ACTA2, CCNB1, CDC20 and VEGFA were associated with the prognosis of patients with bladder cancer." (PMID 30533316, 2018). "Weighted gene co-expression network analysis (WGCNA), protein–protein interaction (PPI) network mutual analysis, and the Kaplan–Meier survival prognosis analysis were used to identify six key genes associated with the prognosis of bladder cancer: VEGFA, ANXA1, HSP90B1, PSMA7, PRDX6, and PPP1CB." (PMID 36741702, 2022). "Besides, circRNA-MYLK, whose expression is upregulated in bladder cancer and positively associated with advanced clinical stage, behaves as a miR-29a sponge to upregulate VEGF expression inducing VEGFA/VEGFR2 signaling pathway which consequently promotes EMT and angiogenesis in bladder cancer." (PMID 36114510, 2022). "Recent studies suggest that TANs can secrete MMP9 and VEGFA, contributing to lymphatic vessel formation and LN metastasis in cancers such as bladder cancer." (PMID 40739091, 2025). "YB-1 promotes angiogenesis in bladder cancer (BC) by downregulating miR-29b-3p, thereby upregulating VEGFA expression." (PMID 39860039, 2025). "The concurrent inhibition of PGF and VEGFA stands out as the only intervention capable of significantly enhancing the infiltration of CD8+ cytotoxic T cells within the bladder cancer microenvironment." (PMID 39628692, 2024). "Another limitation of our study was a lack of tissue available for follow-up experiments to confirm the interaction between GPNMB and VEGFA in bladder cancer." (PMID 38890455, 2024). "Future works should focus on developing drugs specifically inhibiting PGF signaling or, ideally, PGF and VEGFA, and on exploring the synergistic effects of combining these drugs with immunotherapy for more effective clinical treatments of bladder cancer." (PMID 39628692, 2024). "We found that PGF is an additional pro-angiogenic factor in bladder cancer, complementing the well-known role of VEGFA." (PMID 39628692, 2024). "For example, in bladder cancer cells, autophagy induces the secretion of extracellular vesicles, increases vascular endothelial growth factor A(VEGFA)expression, and facilitates angiogenesis." (PMID 38576024, 2024). "A study found that miR-299-3p suppresses bladder cancer progression by downregulating VEGFA levels and inhibiting angiogenesis." (PMID 39628486, 2024). "We observed that Sig1R and β1-integrin affected VEGFA secretion and promoted the angiogenic capacity of bladder cancer cells." (PMID 37199665, 2023). "The aim of this study was to evaluate the promoter mutational status of VEGFA and the expression levels of VEGFA, VEGFR1, and VEGFR2 in bladder cancer (BC) tissues and to correlate the results with the clinical–pathological parameters of BC patients." (PMID 37189572, 2023). "CircRNAs have prognostic value in bladder cancer and can regulate VEGFA expression to affect the formation of bladder cancer." (PMID 37234708, 2023). "Overexpression of some angiogenesis factors was associated with bladder cancer metastasis and poor prognoses, such as hypoxia-inducible Factor-1α (HIF-1α), vascular endothelial growth factor A (VEGFA), and fibroblast growth factor (FGF)." (PMID 37988196, 2023). "The Kaplan–Meier survival prognosis analysis was performed on the top 100 genes, and 6 genes related to the survival prognosis of bladder cancer were finally screened out: VEGFA, ANXA1, HSP90B1, PSMA7, PRDX6, and PPP1CB." (PMID 36741702, 2022). "According to BC values and the Kaplan–Meier survival curve, six genes related to the occurrence and development of bladder cancer were screened out: VEGFA, ANXA1, HSP90B1, PSMA7, PRDX6, and PPP1CB." (PMID 36741702, 2022).
bladder cancer (continued). "The expression of VEGFA in bladder cancer specimens was substantially increased compared to those of normal mucosa and is regarded as a predictively prognostic biomarker in bladder cancer." (PMID 35203290, 2022). "VEGFA was most enriched in bladder cancer, and VCL was highly related to vascular smooth muscle contraction." (PMID 34112125, 2021). "High expression levels of FOXO3, EGFR, and GPC1 as well as low expressions of VEGFA were closely correlated with poorer survival outcomes of bladder cancer patients." (PMID 33962639, 2021). "Univariate analysis indicated age, race, MMP9, IL8, VEGFA, CA9, PAI1, ApoE, A1AT, ANG and MMP10 were associated with bladder cancer." (PMID 33823873, 2021). "Circ0001429 interacts with miR-205-5p to regulate VEGFA expression, accelerating cell propagation, migration, and invasiveness in bladder cancer." (PMID 32943996, 2020). "A previous study suggested that circRNA MYLK (circMYLK) acts as a ceRNA to promote the proliferation and metastasis of bladder cancer by modulating the VEGFA/VEGFR2 signalling pathway." (PMID 32342645, 2020). "In sera of bladder cancer patients, the pro-inflammatory cytokines IL-6 and IL-8 were also elevated, along with the pro-angiogenic factor VEGFA." (PMID 31717324, 2019). "Survival analysis revealed that the expression levels of ACTA2, CCNB1, CDC20 and VEGFA were related to the prognosis of patients with bladder cancer." (PMID 30533316, 2018). "In bladder carcinoma, circRNA-MYLK directly binds to miR-29a and acts as a ceRNA, which contributes to epithelial–mesenchymal transition and bladder carcinoma development through activating VEGFA/VEGFR2 and its downstream Ras/ERK signaling pathway." (PMID 30486834, 2018). "CircMOT1 sponges miR-9 to suppress HCC progression, circMYLK sponges miR-29a to activate the VEGFA/VEGFR2 pathway to promote bladder cancer progression, and ciRS-7 is involved in a variety of cancers by its interaction with miR-7." (PMID 30336780, 2018). "The labels mean the genes VEGFA, MMP2 and MDM2 from the target gene set of the cancers (C) associated co-function module can be mapped to the Bladder cancer pathway." (PMID 28340554, 2017). "For instance, there are three edges connecting the genes with the pathway ‘hsa05219: Bladder cancer’ together with the labels of “C N VEGFA”, “C N MMP2” and “C MDM2”." (PMID 28340554, 2017). "Mechanistically, KLF5 exerts these functions as a novel pro-angiogenic factor in bladder cancer by directly regulating the transcription of VEGFA, which is the most prominent factor among the angiogenic cytokines." (PMID 26544730, 2015). "Taken together, these data demonstrate that KLF5 regulated bladder cancer angiogenesis through promoting VEGFA expression." (PMID 26544730, 2015). "Our data here not only elucidate the mechanism how KLF5 activates the transcription of VEGFA, but also provide evidence of the correlation between expression of KLF5 and VEGFA in human bladder cancer cell lines and tissues." (PMID 26544730, 2015). "To further verify the importance of KLF5-regulated VEGFA in bladder cancer angiogenesis, we modified VEGFA concentration in the CMs using VEGFA neutralizing antibody MAB293 or recombinant human VEGF165." (PMID 26544730, 2015). "Our results showed a significant overexpression of VEGFA in bladder cancer, verifying the results from previous reports." (PMID 22895562, 2012). "This pathway also regulates VEGFA expression in bladder cancer." (PMID 40316995, 2025). "Notably, the concurrent inhibition of PGF and VEGFA amplifies the therapeutic impact of anti-PD-1 treatment in bladder cancer." (PMID 39628692, 2024). "However, VEGFA expression is reduced during the progression of bladder cancer, altering the use of anti-angiogenic agents that target VEGFA/VEGFR2 signaling." (PMID 39628692, 2024).